CGAS (cyclic GMP-AMP synthase)
Diseases named in the same sentence as CGAS in open-access papers (continued):
Sharing a sentence is not in itself a finding about the gene and the disease.
rheumatoid arthritis (19 papers, 2015 to 2026). A chronic, systemic autoimmune disorder characterized by inflammation in the synovial membranes and articular surfaces. "cGAS expression was also enhanced in RA FLS compared with osteoarthritis FLS and healthy control FLS, with a positive correlation between cGAS expression in tissue and synovitis scores, suggesting an association between cGAS expression and rheumatoid arthritis synovial inflammation." (PMID 37354378, 2023). "For example, increased IFN-I responses mediated by cGAS-STING due to abnormal clearance of cytosolic DNA and RNA have been implicated in the pathogenesis of SLE and aggressive rheumatoid arthritis." (PMID 40894167, 2025). "The first experimental reports linking the cGAS–STING pathway to Akt was based on rheumatoid arthritis." (PMID 34906241, 2021). "Experimental results demonstrated that the cGAS–STING pathway promoted the inflammatory response in rheumatoid arthritis, and when cGAS expression was inhibited, Akt expression was significantly decreased." (PMID 34906241, 2021). "Likewise, the accumulation of dsDNA contributed to FLS-mediated rheumatoid arthritis synovial inflammation, which can be alleviated by the knockdown of cGAS or STING." (PMID 37049889, 2023). "Overactivation of cGAS significantly contributes to the development of both autoimmune and autoinflammatory diseases, including rheumatoid arthritis (RA), AGS, and SLE." (PMID 40470467, 2025). "Exploring therapeutic interventions that target cGAS/STIN holds significant promise, considering the pivotal role of its downstream targets in the pathogenesis of both osteoarthritis and rheumatoid arthritis." (PMID 38765007, 2024). "siRNA knockdown of cGAS or STING reduced cytosolic dsDNA-induced migration and invasion of fibroblast-like synoviocytes (FLSs) obtained from rheumatoid arthritis (RA) patients with diminished formation of lamellipodia." (PMID 37354378, 2023).
cardiac hypertrophy (18 papers, 2021 to 2026). "It has been shown that PA-induced ROS can oxidatively damage mtDNA in mitochondria, causing its leakage, which activates the cGAS-STING pathway, triggers NLRP3-mediated pyroptosis, and ultimately leads to myocardial hypertrophy." (PMID 41020872, 2025). "Endogenous leptin exerts pro-hypertrophic effects on the heart, whereas exogenous leptin has been shown to markedly attenuate cardiac hypertrophy and fibrosis by modulating the cGAS-STING signaling pathway and Opa1-mediated mitochondrial fusion." (PMID 41020872, 2025). "We systematically evaluated the impact of these exercise interventions on cardiac function, myocardial hypertrophy, inflammation, fibrosis, PANoptosis, and activation of the cGAS–STING signaling pathway in DCM mice." (PMID 41008530, 2025). "A growing body of research supports the idea that myocardial hypertrophy and the activation of cardiac inflammation, in which cGAS-STNG plays an important role, are key triggers of HF in humans and animals." (PMID 38720328, 2024). "Cardiac function was improved, and myocardial hypertrophy was reduced after inhibiting cGAS or STING." (PMID 37163421, 2023). "Mechanistic analyses showed that THF mitigated myocardial hypertrophy by suppressing oxidative stress and inhibiting activation of the cGAS-STING pathway, thereby preventing downstream NLRP3 inflammasome-mediated pyroptosis and inflammatory cytokine production." (PMID 41798912, 2026). "Moreover, mouse models have demonstrated that mitochondrial damage and activation of the cyclic GMP-AMP synthase (cGAS)-stimulator of interferon genes pathway induce cardiomyocyte pyroptosis and myocardial hypertrophy." (PMID 40832584, 2025). "In addition, cGAS-and STING-deficient mice reduced myocardial hypertrophy, inhibited inflammatory cell infiltration and inflammatory response, reduced cardiomyocyte apoptosis, and improved survival." (PMID 40520009, 2025). "We further investigated whether cGAS-Sting signaling was involved in Nap1l1 p.D349E-mediated cardiac hypertrophy." (PMID 40169585, 2025). "Others have also demonstrated that the uraemic milieu can trigger activation of the mitogen-activated protein kinase (MAPK), nuclear factor (NF)-κB, and cyclic GMP-AMP synthase (cGAS)-stimulator of interferon genes (STING) pathways which can promote cardiac hypertrophy." (PMID 40944787, 2025). "Furthermore, increasing evidence suggests that inhibiting the cGAS-STING signaling pathway can significantly inhibit myocardial hypertrophy and inflammatory cell infiltration." (PMID 38720328, 2024). "The remarkable mitochondrial oxidative damage to cardiomyocytes in patients with chronic kidney disease (CKD) causes mtDNA leakage, which activates the cGAS-STING-NFκB pathway and NFκB-transactivated ornithine decarboxylase (ODC1)-putrescine metabolic flux, inducing cardiac hypertrophy." (PMID 37163421, 2023). "The results showed that specific knockdown of both cGAS and STING in the heart can effectively improve heart function in DCM mice and inhibit myocardial hypertrophy and heart damage, proving that the cGAS-STING pathway has an important regulatory effect in the hearts of DCM mice after activation." (PMID 35538059, 2022). "In TAC-induced HF, the cGAS-STING signaling pathway is activated, and inhibition of this pathway can down-regulate the early inflammatory response of TAC, reduce myocardial hypertrophy, fibrosis and pyroptosis, and preserve myocardial contractility." (PMID 40520009, 2025). "This release triggers the cGAS-STING pathway, which results in the production of pro-inflammatory cytokines, leading to cardiac hypertrophy by creating a hyper-immune microenvironment." (PMID 40169585, 2025). "A deficiency of the PINK1 protein induced inflammation in mouse myocardium and promoted cardiac hypertrophy, whereas the overexpression of the cardiac-specific PINK1 protein inhibited cGAS-STING signaling and prevented cardiac hypertrophy." (PMID 41241888, 2025).
cardiac hypertrophy (continued). "It has been reported that the cGAS-STING pathway participated in myocardial ischemia-reperfusion injury and cardiac hypertrophy." (PMID 34483919, 2021). "For example, free fatty acid-induced mitochondrial damage and the consequent release of mtDNA can activate cGAS–STING, thereby promoting pyroptosis and pro-inflammatory responses through an NLRP3 inflammasome-dependent mechanism and ultimately contributing to myocardial hypertrophy in DCM." (PMID 41008530, 2025). "Inhibition of cGAS-STING signalling could be beneficial by preventing heart adverse remodelling in many disease settings, including cardiac hypertrophy, diabetic cardiomyopathy and doxorubicin-induced cardiotoxicity." (PMID 40245468, 2025). "Interestingly, when the upstream expression of cGAS was decreased, the survival of mice after TAC improved, with preserved myocardial contractility and attenuated myocardial hypertrophy, fibrosis, and pyroptosis." (PMID 38720328, 2024). "Moreover, cGAS-STING silencing effectively reduced myocardial pyroptosis and inflammation in DCM, further mitigated myocardial hypertrophy, and improved cardiac function." (PMID 35538059, 2022). "Mechanistically, our results demonstrated that lipotoxicity induced by FFAs triggers pyroptosis of myocardial cells through the activation of NLRP3 inflammasome in a cGAS-STING-dependent manner, which contributes to the sterile inflammatory response and myocardial hypertrophy." (PMID 35538059, 2022).
glioma (18 papers, 2020 to 2026). A benign or malignant brain and spinal cord tumor that arises from glial cells (astrocytes, oligodendrocytes, ependymal cells). "In vitro and in vivo assays showed that knockdown of FAM83D resulted in abnormal cell division, which increased double-stranded DNA in the cytoplasm, thereby inducing tumor cell senescence by activating the cGAS-STING signaling to suppress glioma progression." (PMID 41742219, 2026). "Gliomas often suppress or downregulate molecules of the cGAS–STING pathway, diminishing IFN-I production and blocking immune surveillance." (PMID 41157253, 2025). "Inactivating mutations in ATRX have been shown to disrupt immune signaling pathways, such as promoting immunosuppressive mechanisms in IDH1-mutant gliomas and impairing cGAS-STING signaling in sarcomas." (PMID 40495762, 2025). "Combined treatment with oHSV and the HDACi panobinostat enhanced virus replication mediated by the downregulation of IFN-β- and IFN-stimulated antiviral genes, as well as the cGAS/STING pathway in glioma and squamous cell carcinoma cells." (PMID 36560800, 2022). "In summary, combined treatment with oHSV and HDACi panobinostat augmented virus replication, mediated by the downregulation of IFN-β- and IFN-stimulated antiviral genes, as well as the cGAS/STING pathway in glioma and squamous cell carcinoma cells." (PMID 36560800, 2022). "The STING pathway is often inhibited by gliomas through the reduced expression of key components such as cGAS and STING, leading to impaired detection of tumor-derived DNA and lowered production of type I IFN, found to be essential in triggering tumor suppressive responses." (PMID 41157253, 2025). "The remaining living glioma cells might be able to activate cGAS-STING1 pathway and release TNFα." (PMID 37292196, 2023). "Triggering the cGAS/stimulator of interferon genes (STING) pathway with potent agonists, such as 8803, exerts activity across high-grade glioma preclinical models." (PMID 41697735, 2026). "Emerging research highlights the significant role of innate immune receptors including Toll-like, NOD-like and RIG-like receptors, as well as cGAS-STING receptors, scavenger and C-type lectin receptors in glioma development and progression." (PMID 41157253, 2025). "Like RLRs, the cGAS-STING, cyclic GMP-AMP synthase-STING pathway is also a key player in mediating innate immune system responses within gliomas." (PMID 41157253, 2025). "We next explored the correlation for IRAK1 expression with cGAS and STING based on glioma patients from TCGA datasets." (PMID 37031183, 2023). "In this Review, we discuss cGAS/STING signaling in gliomas, its implications for glioma immunobiology, compartment-specific roles for STING signaling in influencing immune surveillance, and efforts to target STING signaling — either directly or indirectly — for antiglioma therapy." (PMID 38226619, 2024). "Quantitative RT-PCR showed that cellular DNA sensors STING, AIM2 and cGAS were not consistently up-regulated in the two stocks of human primary glioma cells upon ADV infection." (PMID 32843056, 2020). "Beyond radiation, and despite a lack of momentum from early-stage clinical trials, targeting the intratumor cGAS/STING axis with specific agonists of STING (e.g., analogs or derivatives of cGAMP) remains of interest in immunologically quiescent cancer types, such as gliomas." (PMID 39621308, 2024).
herpesvirus infection (18 papers, 2016 to 2026). "For example, during herpesvirus infection, mitochondrial stress triggers the release of mtDNA into the cytosol, where it is sensed by cGAS, leading to activation of the STING-IRF3 pathway and subsequent induction of type I interferon responses." (PMID 41522347, 2026). "In conclusion, overlapping peptides from US1 protein of alpha-herpesviruses antagonize cGAS-mediated innate immune responses, highlighting a promising target for the development of broad-spectrum inhibitors to counteract herpesvirus infections." (PMID 41196926, 2025). "The cGAS/STING signaling pathway plays a pivotal role in the course of herpesvirus infection, serving as the primary signaling pathway that recognizes dsDNA signals within the cell and inducing the onset of the major type I interferon response." (PMID 39601590, 2025). "The innate immune response to HSV-1 (or other herpesvirus) infection is initiated primarily by the cGAS, RLR, and TLR signaling pathways." (PMID 39599852, 2024). "In agreement with the role of cGAS in the interferon responses to herpesvirus infection, mouse fibroblasts, macrophages, and dendritic cells lacking cGAS were found to be unable to launch IFN type I responses." (PMID 35458396, 2022). "During herpesvirus infection, viral DNA released into the cytoplasm triggers the activation of the cGAS-STING DNA sensing pathway, which results in the production of IFN-I and inflammatory chemokines to suppress viral replication." (PMID 36287016, 2022). "We describe the activation of cGAS-STING signaling pathway during herpesvirus infections and strategies of herpesvirus targeting this pathway to evade host antiviral response." (PMID 35844623, 2022). "It has been demonstrated that the cGAS-STING axis plays a critical role in the induction of type I IFNs in response to herpesvirus infection." (PMID 35584187, 2022). "Emerging evidence indicates that the cGAS-STING signaling pathway plays an important role in the innate immunity in response to herpesvirus infections." (PMID 35844623, 2022). "Then we describe the activation of cGAS-STING signaling pathway during herpesvirus infections and strategies of herpesvirus targeting this pathway to inhibit and evade the host antiviral response." (PMID 35844623, 2022). "One group took a proteomics-based approach to uncover cGAS interactors in the context of herpesvirus infection, identifying OASL as a cGAS interactor and inhibitor." (PMID 33362792, 2020). "cGAS also induces apoptosis through activating STING-TBK1-IRF3 pathway upon DNA sensing during herpesvirus infection." (PMID 31539404, 2019). "Why the cGAS/STING axis has such divergent roles in two different herpesvirus infections is currently difficult to understand and has to be addressed in future studies." (PMID 31249303, 2019). "In contrast, we find that, upon DNA sensing during herpesvirus infection, cGAS triggers apoptosis in a STING-dependent manner." (PMID 27935834, 2016). "None of the differentially regulated genes were linked to antiviral immunity associated with herpesvirus infections (for example, MX2, IFI16, CGAS, IFITs and OASs32,82–84), indicating that the anti-VZV function of NPHP4 is probably independent of the innate immune defence." (PMID 40739040, 2025). "In present study, we emphasize the role of the cGAS-STING pathway in various systemic diseases by briefly summarizing its role in diseases occurrence, and emphatically discussing the research progress on the cGAS-STING pathway in anti-human herpesvirus infections." (PMID 37600809, 2023). "The cGAS-STING signaling pathway is activated during herpesvirus infections." (PMID 35844623, 2022). "Because herpesviruses are DNA viruses that induce ROS and engage the cGAS/STING pathway, we hypothesized that ROS antagonize the production of interferon downstream of cGAS/STING during herpesvirus infection." (PMID 32886065, 2020).
herpesvirus infection (continued). "This study is the first to report that cGAS mediates induction of miR-26a in herpesvirus infection." (PMID 31861450, 2019). "This article discusses the role of the cGAS-STING pathway in human diseases, especially in human herpesvirus infections, as well as highlights how these viruses act on this pathway to evade the host immunity." (PMID 37600809, 2023). "Other studies revealed that both cGAS and IFI16 are required for the IFN responses to herpesvirus infections." (PMID 35458396, 2022). "The cGAS-STING signaling pathway is critical to drive the initial IFN-I response and limite herpesvirus infection." (PMID 35844623, 2022). "Interestingly, MyD88 deficient patients do not show enhanced susceptibility to herpesvirus infections, but under such conditions a functional cGAS/STING axis might be essential to compensate for the loss of TLR signaling." (PMID 31249303, 2019). "In this review, we summarize recent advances in the modulation of innate immune signaling by TRIM proteins during herpesvirus infection, with a focus on the detection of herpes simplex virus type 1 (HSV-1, a prototype herpesvirus) by cGAS-STING, RIG-I-like receptors, and Toll-like receptors." (PMID 39599852, 2024). "The cGAS-STING signaling pathway is indispensable for the sensing of herpesvirus in host innate immunity, which makes this pathway an important candidate target for the therapy of herpesvirus infections." (PMID 35844623, 2022). "It is speculated that perhaps, rather than cGAS directly detecting viral DNA, cGAS rather detects mitochondrial DNA which is released due to herpesvirus infections." (PMID 32708188, 2020).